ALPL (alkaline phosphatase, biomineralization associated)
Diseases named in the same sentence as ALPL in open-access papers (continued):
Sharing a sentence is not in itself a finding about the gene and the disease.
hypophosphatasia (continued). "In fact, hypomorphic mutations in the ALPL gene encoding TNAP lead to accumulation of PPi in the extracellular matrix with deficits in bone mineralization, causing hypophosphatasia, a heritable form of rickets in children or osteomalacia in adults (Whyte, 2010)." (PMID 29375373, 2017). "Mild hypophosphatasia (HPP) phenotype may result from ALPL gene mutations exhibiting residual alkaline phosphatase activity or from severe heterozygous mutations exhibiting a dominant negative effect." (PMID 19500388, 2009). "Hypophosphatasia (HPP) is a rare, inherited, multisystemic disease manifesting due to mutations in the ALPL gene (1p36.12, NCBI-Gene-ID: 249)." (PMID 40530336, 2025). "Hypophosphatasia (HPP) is the inborn error of metabolism caused by pathogenic or likely pathogenic variants in the ALPL gene." (PMID 40224914, 2025). "Hypophosphatasia (HPP) is an uncommon metabolic disorder induced by a mutation in the alkaline phosphatase (ALPL) gene affecting the liver, bones, and/or kidneys." (PMID 40136761, 2025). "Hypophosphatasia (HPP) is a rare genetic disorder mainly affecting bone and tooth mineralization in patients due to ALPL gene mutations." (PMID 40962875, 2025). "Hypophosphatasia (HPP) is a rare inherited bone disorder caused by ALPL gene mutations, leading to reduced alkaline phosphatase (ALP) activity and impaired bone mineralization." (PMID 40600080, 2025). "Early-onset bone dysplasia is a common manifestation of hypophosphatasia (HPP), an autosomal inherited disease caused by ALPL mutation." (PMID 38609899, 2024). "Hypophosphatasia (HPP) is an inherited disease caused by ALPL mutation, resulting in decreased alkaline phosphatase (ALP) activity and damage to bone and tooth mineralization." (PMID 37107680, 2023). "Also, it is unclear if there are clinical differences between adult patients with hypophosphatasia (this is, with a deleterious mutation of ALPL) and those with low alkaline phosphatase of unknown cause." (PMID 36072928, 2022). "Hypophosphatasia (HPP) is a rare, and usually diagnosed with delay, genetic disease caused by a mutation in the alkaline phosphatase liver/bone/kidney type (ALPL) gene." (PMID 35453912, 2022). "Hypophosphatasia (HPP) is an inherited disease caused by mutation of the alkaline phosphatase (ALPL) gene in an autosomal dominant or an autosomal recessive manner." (PMID 36553293, 2022). "Hypophosphatasia (HPP), a skeletal disease characterized by hypomineralization of bone and teeth, is caused by an ALPL gene mutation that leads to low activity of the tissue non-specific alkaline phosphatase enzyme." (PMID 34176466, 2021). "Hypophosphatasia (HPP) is caused by loss‐of‐function mutations in ALPL resulting in decreased alkaline phosphatase (ALP) activity." (PMID 34189384, 2021). "Altered dimerization can result in dominant negative effects of heterozygous mutations in the ALPL gene, which has already been described in the context of Hypophosphatasia (HPP) patients." (PMID 33477631, 2021). "The loss-of-function mutations in the ALPL result in hypophosphatasia (HPP), an inborn metabolic disorder that causes skeletal mineralization defects." (PMID 32351759, 2020). "Hypophosphatasia (HPP) is an inborn error of metabolism, caused by mutation of the gene ALPL that encodes the enzyme tissue non‐specific alkaline phosphatase." (PMID 31687651, 2019). "Hypophosphatasia (HPP) is a rare heritable metabolic bone disease caused by hypomorphic mutations in the ALPL (in human) or Akp2 (in mouse) gene, encoding the tissue-nonspecific alkaline phosphatase (TNAP) enzyme." (PMID 29551976, 2018). "Hypophosphatasia (HPP) is a rare inherited metabolic disorder caused by the low activity of the enzyme tissue-non-specific alkaline phosphatase (TNSALP) due to loss-of-function pathogenic variants of the ALPL gene (1p36.12)." (PMID 40114282, 2025).
hypophosphatasia (continued). "Hypophosphatasia (HPP) is a rare metabolic bone disorder caused by functional mutations in the gene Alkaline Phosphatase, Liver/Bone/Kidney (ALPL), resulting in impaired mineralization of bones and teeth." (PMID 40756947, 2025). "Hypophosphatasia (HPP) is a rare inherited metabolic disease characterized by low activity of tissue-nonspecific alkaline phosphatase (TNAP) due to pathogenic variants in the ALPL gene." (PMID 40906226, 2025). "Hypophosphatasia (HPP) is a rare inherited disorder characterized by a deficiency of tissue-non-specific alkaline phosphatase (TNSALP) due to loss-of-function variants of the ALPL gene." (PMID 40114282, 2025). "Loss of function mutations (mostly missense) in the TNALP gene ALPL, expressing BALP, cause hypophosphatasia (HPP; OMIM#: 146300, 241500, 241510), which is a rare inborn-error-of-metabolism." (PMID 35631265, 2022). "Genetically inheritable TNAP dysfunction, due to mutations in the ALPL gene, leads to the rare disease Hypophosphatasia (HPP)." (PMID 33477631, 2021). "Premature exfoliation of the deciduous teeth is a common manifestation in childhood patients with hypophosphatasia (HPP), which is an autosomal inherited disease caused by ALPL mutations." (PMID 33823913, 2021). "Hypophosphatasia (HPP) is a rare inherited disorder, which is caused by loss-of-function mutations in the ALPL gene." (PMID 33827627, 2021). "Hypophosphatasia (HPP) is a rare and intractable metabolic bone disease caused by mutations in the ALPL gene." (PMID 31600233, 2019). "The evaluation of ALP substrates in patients with low ALPL levels allows the identification of patients with hypophosphatasia." (PMID 30680361, 2019). "In conclusion, we identified the SNP c.787T>C in the ALPL gene in a Chinese family with hypophosphatasia." (PMID 28881669, 2017). "This led to the consideration of a diagnosis of hypophosphatasia, which was confirmed by genetic analysis, identifying a pathogenic variant NM_000478.6(ALPL) .892G>A p.(Glu298Lys) in the gene encoding tissue-nonspecific alkaline phosphatase (TNSALP)." (PMID 41503045, 2026). "This case demonstrates the relevance of the Kocher criteria in metabolic chest deformities and underscores the role of surgery in ALPL-related hypophosphatasia by interrupting the cycle of thoracic deformity, restrictive lung disease, and impaired bone metabolism." (PMID 40703321, 2025). "Hypophosphatasia (HPP) is a rare inherited metabolic disorder characterized by deficient activity of tissue-nonspecific alkaline phosphatase (TNAP) caused by variants in the ALPL gene." (PMID 40047955, 2025). "Hypophosphatasia (HPP) is a rare inborn error of metabolism caused by pathogenic variants in ALPL, coding for tissue non-specific alkaline phosphatase." (PMID 40244092, 2025). "Patient 10, carrying a pathogenic ALPL gene mutation consistent with hypophosphatasia, received vitamin D supplementation alone, without additional calcium supplementation or bisphosphonate therapy." (PMID 41517371, 2025). "Hypophosphatasia (HPP) is an inborn error of metabolism caused by loss-of-function variants in the ALPL gene, which encodes the tissue nonspecific isozyme of alkaline phosphatase (ALP)." (PMID 40224914, 2025). "However, we also found variants in genes associated with primary hyperparathyroidism (GCM2), renal hypophosphatemia with or without rickets (SLC34A1, SLC34A3, SLC9A3R1, VDR, and CYP27B1), DiGeorge syndrome (TBX1 and NEBL), and hypophosphatasia (ALPL)." (PMID 38586466, 2024). "Pyrophosphate deposition in hypophosphatasia can be explained: in physiological conditions, ALPL converts inorganic pyrophosphate (PPi) to inorganic phosphate (Pi), which can complex with ionized calcium and constitute hydroxyapatite crystals, required for correct mineralization." (PMID 38673536, 2024). "Hypophosphatasia is an inborn error of metabolism caused by reduced or absent activity of the TNSALP enzyme, resulting from pathogenic variants of the ALPL gene." (PMID 38673536, 2024).
hypophosphatasia (continued). "Hypophosphatasia (HPP) is a rare genetic disorder in which pathogenic variants of the ALPL gene lead to a marked decrease of tissue non-specific alkaline phosphatase (TNSALP) activity." (PMID 37752373, 2024). "Hypophosphatasia (HPP) is a rare inherited disorder characterized by the decreased activity of tissue-nonspecific alkaline phosphatase (TNSALP), caused by mutations in the ALPL gene." (PMID 39519277, 2024). "Hypophosphatasia (HPP) is a heritable metabolic disorder characterized by mutations in the ALPL gene that encodes tissue non-specific alkaline phosphatase (TNAP), an enzyme found in a variety of tissues including kidneys, liver, brain, and bone." (PMID 37958888, 2023). "Hypophosphatasia was diagnosed based on clinical and laboratory findings and ALPL genetic results." (PMID 36911640, 2023). "The Akp2−/− model mice carries the phenotype of severe human infantile hypophosphatasia (HPP), exhibiting fetal skeletal dysplasia, growth and respiratory failure, bone hypomineralization, seizures and death by two postnatal weeks caused by ALPL mutations." (PMID 36965009, 2023). "Hypophosphatasia (HPP) is a rare systemic genetic disorder resulting from mutations in ALPL gene (also known as TNSALP), which encodes the tissue-nonspecific isoenzyme of alkaline phosphatase (TNSALP) and leads to diminished ALP activity." (PMID 37818127, 2023). "Hypophosphatasia (HPP) is a rare, inherited disorder associated with low alkaline phosphatase (ALP) due to tissue-nonspecific alkaline phosphatase (TNSALP) deficiency resulting from > 400 genetic aberrations in ALPL." (PMID 35854311, 2022). "Hypophosphatasia (OMIM #171760) is caused by inactivating mutations in the tissue non-specific isoenzyme of alkaline phosphatase (TNSALP) encoded by the ALPL gene." (PMID 33990852, 2022). "Mutation in the ALPL or RSK2 gene causes defective development of non-cellular cementum or its absence in patients suffering from hypophosphatasia or Coffin–Lowry syndrome, which leads to PDL detachment, tooth mobility, and tooth loss." (PMID 35329073, 2022). "Hypophosphatasia (HPP) is a rare inborn error of metabolism caused by a dysfunction of the tissue nonspecific alkaline phosphatase isoenzyme (TNSALP), which is encoded by ALPL." (PMID 33191482, 2021). "Hypophosphatasia (HPP) is a rare genetic disorder caused by loss-of-function mutations in the ALPL gene encoding tissue nonspecific alkaline phosphatase." (PMID 33579333, 2021). "For example, mice and humans with inactivated ALPL gene mimic a severe form of hypophosphatasia." (PMID 34198561, 2021). "Hypophosphatasia (HPP) is a rare inherited disorder characterized by rickets and low circulating concentrations of total alkaline phosphatase (ALP) caused by mutations in ALPL." (PMID 31793067, 2020). "ALPL gene analysis is expected to reveal a defect in all patients with hypophosphatasia." (PMID 30864637, 2019). "Although hypophosphatasia can typically be diagnosed without ALPL mutation analysis, this information is crucial for understanding inheritance." (PMID 30864637, 2019). "Hypophosphatasia (HPP) is a rare disease caused by mutations in the ALPL gene encoding tissue-non-specific isoenzyme of alkaline phosphatase (TNSALP)." (PMID 30468149, 2019). "Hypophosphatasia is caused by low activity of the tissue non-specific isoenzyme of alkaline phosphatase (TNSALP) caused by a mutation in the ALPL gene." (PMID 30209646, 2018). "Besides skeletal symptoms, dental abnormalities are a typical feature of the rare inherited disorder hypophosphatasia (HPP), which is caused by loss of function mutations in the ALPL gene (alkaline phosphatase, biomineralization associated) coding for tissue-nonspecific alkaline phosphatase (TNAP)." (PMID 40530336, 2025).
hypophosphatasia (continued). "Hypophosphatasia (HPP) is the inherited metabolic disease caused by mutations in the ALPL gene encoding tissue-nonspecific alkaline phosphatase (TNSALP) and is characterized by impaired mineralization of bones caused by low levels of alkaline phosphatase (ALP) activity." (PMID 35075203, 2022). "PPi inhibits the formation of apatite crystals as evidenced by hypomorphic mutations of tissue-nonspecific alkaline phosphatase (TNAP) gene (ALPL), which impair PPi hydrolysis and lead to the accumulation of extracellular PPi that cause the soft bones disease known as hypophosphatasia." (PMID 36499456, 2022). "This review summarizes important information on the ectoenzyme tissue-nonspecific alkaline phosphatase (TNAP) and gives a brief insight into the symptoms, diagnostics, and treatment of the rare disease Hypophosphatasia (HPP), which is resulting from mutations in the TNAP encoding ALPL gene." (PMID 33477631, 2021). "This is the case of a genetically inheritable TNAP alteration, due to mutations in the ALPL gene leading to the rare disease hypophosphatasia (HPP) in humans." (PMID 33946568, 2021). "Hypophosphatasia (HPP) is an inherited metabolic disease, characterized by low activity of tissue non-specific alkaline phosphatase (TNAP) due to mutations at the ALPL gene." (PMID 34884378, 2021). "Patients with inherited loss of function mutations in the ALPL gene and consequently altered TNAP activity are suffering from the rare metabolic disease hypophosphatasia (HPP)." (PMID 33302551, 2020). "Hypophosphatasia (HP) is a rare inherited disorder characterized by a wide spectrum of defects in mineralized tissues and caused by deficiency in the tissue non-specific alkaline phosphatase gene (ALPL)." (PMID 19232125, 2009). "Finally, we do not know if the pathogenic ALPL variation in patient 4 could have modified his clinical presentation as hypophosphatasia may be associated with hypercalcemia and hypercalciuria." (PMID 40765620, 2025). "Hypophosphatasia (HPP) is a rare, inherited monogenic disorder that is typically caused by variants in the tissue‐nonspecific alkaline phosphatase (ALPL) gene." (PMID 41047464, 2025). "Hypophosphatasia (HPP) is a rare inherited disorder of bone mineralization caused by mutations in the ALPL gene, which encodes the tissue-nonspecific alkaline phosphatase (TNSALP)." (PMID 40600080, 2025). "Hypophosphatasia (HPP) is a rare inborn-error-of-metabolism caused by mutations in the ALPL gene, resulting in deficient activity of tissue-nonspecific alkaline phosphatase and impaired skeletal mineralization." (PMID 40894392, 2025). "Hypophosphatasia (HPP) is a genetic disease caused by loss-of-function mutations in ALPL, which encodes tissue-nonspecific alkaline phosphatase (ALP)." (PMID 36820543, 2023). "Hypophosphatasia (HPP) is a hereditary metabolic bone disorder caused by loss-of-function pathogenic variants of the ALPL gene that encodes tissue-nonspecific-isoenzyme of alkaline phosphatase (TNSALP)." (PMID 37731773, 2023). "Hypophosphatasia (HPP) is an inherited, systemic disorder, caused by loss-of-function variants of the ALPL gene encoding the enzyme tissue non-specific alkaline phosphatase (TNSALP)." (PMID 36414794, 2023). "Hypophosphatasia (HPP) is an inherited disease caused by variants of the ALPL gene encoding tissue-nonspecific alkaline phosphatase." (PMID 38130758, 2023). "Hypophosphatasia (HPP) is a hereditary disease that is caused by dysfunction of tissue-nonspecific alkaline phosphatase (TNSALP) caused by mutations in its encoding gene ALPL." (PMID 37147467, 2023). "Hypophosphatasia (HPP) is an inborn metabolic error caused by mutations in the ALPL gene encoding tissue non-specific alkaline phosphatase (TNSALP) and leading to decreased alkaline phosphatase (ALP) activity." (PMID 38234425, 2023).
hypophosphatasia (continued). "Hypophosphatasia (HPP) a rare disease caused by mutations in the ALPL gene encoding for the tissue-nonspecific alkaline phosphatase protein (TNSALP), has been identified as a potentially under-diagnosed condition worldwide which may have higher prevalence than currently established." (PMID 35498405, 2022). "Hypophosphatasia (HPP) is a rare, inheritable, metabolic bone disorder, attributed to loss-of-function mutations in the ALPL gene on chromosome 1 (1p36.12), which encodes for the TNSALP." (PMID 36304528, 2022). "Hypophosphatasia (HPP) is a rare inherited metabolic disorder caused by mutations in the ALPL gene, which encodes tissue nonspecific alkaline phosphatase." (PMID 35197081, 2022). "Disorders of ALP activity are caused by a reduced/absent ALP function (hypophosphatasia, HPP), due to inactivating mutations of the ALPL gene, and are characterized by hypomineralization of hard tissues." (PMID 34638624, 2021). "Mutations in tissue-nonspecific alkaline phosphatase (TNAP), encoded by the ALPL gene, result in the inherited mineralization defect, hypophosphatasia (HPP; OMIM#146300, 241500, 241510)." (PMID 34368800, 2021). "Hypophosphatasia (HPP) is a rare, inherited metabolic disorder caused by loss-of-function mutations in the ALPL gene that encodes the tissue-nonspecific alkaline phosphatase TNAP (ORPHA 436)." (PMID 32811521, 2020). "Hypophosphatasia (HPP) is a rare, metabolic bone disease caused by mutation of the ALPL gene, which encodes tissue-nonspecific alkaline phosphatase (ALP) in bone osteoblasts, and liver, kidney, and skin fibroblasts." (PMID 31600233, 2019). "Hypophosphatasia (HPP) is a genetic disease caused by one or several mutations in ALPL gene encoding the tissue-nonspecific alkaline phosphatase affecting the mineralization process." (PMID 31267001, 2019). "Hypophosphatasia (HPP) is an inborn error of metabolism that is caused by mutations of the ALPL gene, which encodes the tissue nonspecific alkaline phosphatase (TNSALP) isoenzyme." (PMID 30012160, 2018). "We successfully generated the first large animal model of a rare human bone disease, hypophosphatasia (HPP) using CRISPR/Cas9 to introduce a single point mutation in the tissue nonspecific alkaline phosphatase (TNSALP) gene (ALPL) (1077 C > G) in sheep." (PMID 30446691, 2018). "Osteogenesis imperfecta (OI) is a hereditary connective tissue disorder primarily caused by pathogenic variants in type I collagen genes, while hypophosphatasia (HPP) is a metabolic bone disease resulting from reduced activity of tissue-nonspecific alkaline phosphatase (ALP) due to ALPL variants." (PMID 42220822, 2026). "Hypophosphatasia (HPP) is a rare inborn error of metabolism that affects the development of bones and teeth and is caused by pathogenic variants in the ALPL gene, coding for the tissue-nonspecific isozyme alkaline phosphatase (TNSALP, EC:3.1.3.1)." (PMID 40244092, 2025). "While we did not observe a female-biased tau pathway, the rs121918007 missense variant on ALPL, a.k.a. tissue-nonspecific Alkaline Phosphatase (TNAP), causes hypophosphatasia, a metabolic disorder affecting bone mineralization." (PMID 41282793, 2025). "Hypophosphatasia (HPP) is a rare inherited, metabolic disease caused by variants in the gene ALPL, which encodes tissue-nonspecific alkaline phosphatase (ALP)." (PMID 41286962, 2025). "Hypophosphatasia (HPP) is a rare disease caused by deficient activity of tissue-nonspecific alkaline phosphatase (ALP), encoded by the ALPL gene." (PMID 39276275, 2024). "Hypophosphatasia (HPP) is a rare, metabolic disease caused by deficient activity of the enzyme tissue-nonspecific alkaline phosphatase (ALP), encoded by the ALPL gene." (PMID 39276275, 2024). "Hypophosphatasia (HPP) is a rare, inherited, metabolic disease caused by loss of function variants in the ALPL gene resulting in deficiency of tissue-nonspecific alkaline phosphatase (TNSALP)." (PMID 38236379, 2024).